RNU6-546P (RNA, U6 small nuclear 546, pseudogene)
Gene: Small nuclear RNA gene on chromosome 2 (155,330,421 to 155,330,527, forward strand). Ensembl gene ENSG00000206718.
Homologues: Orthologues: chimpanzee U6 (97% identical), macaque U6 (88% identical), rabbit U6 (87% identical), rabbit U6 (83% identical), rat U6 (79% identical). Paralogues in human: RNU6-1 (89% identical), RNU6-144P (89% identical), RNU6-2 (89% identical), RNU6-3P (89% identical), RNU6-4P (89% identical), RNU6-5P (89% identical), RNU6-6P (89% identical), RNU6-9 (89% identical), RNU6-11P (88% identical), RNU6-12P (88% identical), RNU6-13P (88% identical), RNU6-16P (88% identical), and 1288 more.